AR (androgen receptor)
Diseases named in the same sentence as AR in open-access papers (continued):
Sharing a sentence is not in itself a finding about the gene and the disease.
tumor (continued). "Recent immunohistochemical data indicate that this tumor type is generally negative for classical hormone receptors such as estrogen receptor (ER) and progesterone receptor (PR), while frequently expressing androgen receptors (AR), corresponding to an ER−/PR−/AR+ profile." (PMID 40895660, 2025). "Recent studies have demonstrated that the inhibition of AR protein expression using AR inhibitors enzalutamide, abiraterone, or antisense oligonucleotide (ASO) combined with AKT inhibitors AZD5363 and ipatasertib could effectively impede tumor cells progression." (PMID 39485722, 2024). "Considering the ubiquitous expression of ACK1 and SHP2 (and AR in certain compartments) in the immune cells, and ACK1 regulating SHP2 activation, it may prove insightful to examine the role of this signaling nexus in immune cells within the tumor microenvironment." (PMID 38965223, 2024). "Consequently, during the tumour progression, two different phenotypes can be developed: androgen-responsive, where AR always acts as a driver gene, or androgen-insensitive, independent of AR activity." (PMID 38254687, 2024). "Similarly, over-expression of AZGP1 did not affect tumor growth for AR-positive 22Rv1 cells." (PMID 38659028, 2024). "Evidence suggests that AR activation may play a protective role in conjunction with the transcription factor FOXO3a promoting FLICE-inhibitory protein (FLIP, an inhibitor of death receptor-mediated apoptosis) expression in LNCaP cells as well as a protective role for tumor cells." (PMID 37894767, 2023). "However, the castration level of androgens and overexpression of AR leads to increased sensitivity of CRPC cells to supraphysiological levels of androgens, further inhibiting DNA replications and inducing double-strand DNA breaks, inhibiting tumor cell growth, and promoting apoptosis." (PMID 37113653, 2022). "AR antagonist in vitro testing in five different LAR cell line models showed high sensitivity to 17-dimethylaminoethylamino-17-demethoxygeldanamycin (17-DMAG) and bicalutamide treatment, thus indicating that AR targeting therapies may be effective against LAR tumours." (PMID 36077812, 2022). "However, in ERα-negative/AR-positive cells, they accelerate tumor growth." (PMID 35013318, 2022). "Controversies have emerged as to whether ERG activates or attenuates the AR signaling, leading to the hypothesis that ERG can promote the oncogenic functions of AR (e.g., promoting survival of the prostate cells) while inhibiting the tumor-suppressing ones (e.g., differentiation)." (PMID 35267426, 2022). "There is also evidence that PCSCs might come from the basal cell layer, because tissue-derived tumor-initiating cells in immunocompromised mice expressed basal markers (such as p63), but did not express the androgen receptor (AR) or markers of luminal differentiation (PSA and PAP)." (PMID 35875084, 2022). "However, a mixture of AR-positive or -negative neuroendocrine phenotypes, or indeed AR-negative non-neuroendocrine PCa, have been seen, with varying degrees of heterogeneity within each tumor." (PMID 36551674, 2022). "Since AR is anti-proliferative, its use as a potential target for curbing uncontrollable cellular hypertrophy is implied however this might not be the case for all tumors and more studies on tumor endocrinology is needed." (PMID 35372016, 2022). "However, our in vitro and in vivo functional data revealed similar effects on 3D organoid formation and a reduction in tumor growth upon UGT2B28 KD, both in a ligand-driven and castrated AR signaling environment, which suggests that UGT2B28 may have non-canonical roles in prostate tumorigenesis." (PMID 35954173, 2022).
tumor (continued). "In addition to the stimulation of AR by androgen produced from the adrenal gland and testis, intra-tumoral secretion of enzymes involved in the synthesis of testosterone such as cytochrome P450 17-alpha hydroxysteroid dehydrogenase (CYP17) support tumor survival and growth." (PMID 34771580, 2021). "Since p38 MAPK inhibition by SB203580 could block Hsp27 phosphorylation, reduce expression of AR-driven gene expression and inhibit cell proliferation and survival in normoxia and hypoxia, we sought to determine whether SB203580 could also inhibit tumor growth in V16D xenografts." (PMID 33671134, 2021). "Treatment of PCa tumours containing the amplified AR with AR antagonists such as Enzalutamide, Apalutamide and Darolutamide may be ineffective as, although the drugs are still specific to the AR, they may not be able to antagonise all AR proteins." (PMID 33993099, 2021). "However, the positive effect of AR on tumor development is not restricted in ligand-induced AR." (PMID 31896509, 2020). "Therefore, dual targeting of the AR and PI3K may produce a synergistic anti-tumor effect." (PMID 32982970, 2020). "Moreover, overexpression of AR inhibits the PTC cell migration activity and decreases the EMT markers; thereby suggesting that decreasing AR expression may promote the EMT process during the initiation of tumor metastasis or progression." (PMID 32365531, 2020). "However, the present data may indicate that the response to novel AR-targeted drugs may not be related to a high or low tumor burden but may rather depend on the AR dependency of the tumor." (PMID 30978937, 2019). "In conclusion, the finding that AR-V expression levels increase in patients treated with androgen-deprivation therapy might indicate that there is a clonal selection pressure on the different tumour clones in order to maintain functional AR signalling independent of the androgen levels." (PMID 29988112, 2018). "Additionally, the activation of the PI3K/Akt pathway with interaction with AR, which shows some prognostic impact in SDC, implies that it has the potential to be a biomarker of tumor aggressiveness, which may be useful for selecting hormonal and targeted therapy." (PMID 29416736, 2018). "In addition, any tumour exhibiting negative staining for pARS578 was demonstrated to have positive staining for other AR phosphorylation sites confirming that the negative expression was a true negative and not due to phospho-proteins being degraded in that particular sample." (PMID 27902483, 2017). "Furthermore low/no AR expression was related to higher tumor extent in ccRCCs." (PMID 29108248, 2017). "Moreover, it was concluded that the AR antagonist enzalutamide could be used for treatment of AR+ tumors regardless of ER status, since it can block both AR- and ER-mediated tumor growth." (PMID 29083379, 2016). "However, AR DNA-seq read coverage in tumours C-6A and C-6B was indistinguishable." (PMID 27897170, 2016). "Therefore, inhibiting ARVs expression by blocking GRP/GRP-R signaling may not be sufficient to control AR negative NE tumor growth." (PMID 27542219, 2016).
tumor (continued). "An inverse relationship between Androgen Receptor (AR) and c-MET has been already demonstrated suggesting that a reduction of AR activity through androgen ablation may increase the expression of c-MET, directly contributing to androgen insensitivity and favoring tumor aggressiveness." (PMID 26887047, 2016). "We observed an overexpression of both AMACR and AR mRNA in not only cancerous, but also in histologically benign tissue from prostates with clinically significant carcinomas when they were compared to prostates without tumor or harboring only incidental lesions." (PMID 26928323, 2016). "The lack of association between AR CN gene and PSA response rate could have an explanation in possible changes of tumor biology during enzalutamide that were not present before treatment (e.g. neuroendocrine differentiation), even if a bias due to the small sample size needs to be considered." (PMID 27191887, 2016). "A recent CTC transcriptome analysis has demonstrated that non-canonical Wnt signaling associates with enzalutamide drug resistance, and preclinical models suggest that WNT5A, a ligand of the non-canonical Wnt pathway, may abrogate the anti-tumor effects of AR inhibition." (PMID 26566796, 2015). "Finally, it should be noted that down-regulation of miR-34a by XRN1 might contribute to PCa progression independent of AR, since miR-34a can act as a tumor suppressor through directly inhibiting CD44 in tumorigenic and metastatic PCa stem cells." (PMID 25797256, 2015). "We show that tumor cells derived from wild-type animals do not proliferate when transplanted in a Postn-null environment but that this growth defect is rescued by the overexpression of active Notch or the AR target gene prolactin-induced protein (PIP/GCDFP-15)." (PMID 25592291, 2015). "Thus, ours are the first study to indicate that expression of PD-L1 on tumor cells may be a unique mechanism of ENZ resistance that is independent of AR re-activation and not observed in CRPC." (PMID 25428917, 2015). "A novel cancer phenotype in which mice lacking hepatic androgen receptor (AR) developed more undifferentiated tumors and larger tumor size at the metastatic stage, which AR could orchestrate intrahepatic signaling hierarchies and cellular behaviors, consequently affect HCC progression." (PMID 23484104, 2013). "Therefore, the fluctuation in the expression of PSA and PSMA between poorly differentiated PC cases that expressed the RKIP and those lacking this molecule may be connected to the level of AR and/or androgen present in the tumor microenvironment." (PMID 23991415, 2013). "However, few of these may include faulty patient subset selection criteria, no monitoring of tumor ER and AR expression at the time of recruitment and also during treatment of these patients and lastly the type of hormonal treatment given to the patient." (PMID 23484104, 2013). "As such, early targeting of theGLI oncoproteins may impede progression to a hormone independent state, but thisapproach may not enhance the efficacy of anti-hormonal therapy in tumour cells thathave lost AR expression and that are not dependent upon its signalling for theirviability." (PMID 21633508, 2011). "It was reported that loss of maspin expression during tumor progression resulted from both the absence of transactivation through the Ets element and the presence of transcription repression through the negative hormonal responsive element (HRE) recognized by androgen receptor." (PMID 21439064, 2011). "The expression of Ebp1, AR, Cyclin D1, ErbB3 and Ki67 were evaluated by immunohistochemistry using three separate tissue micro-arrays containing normal prostate tissues, non-cancerous tissue adjacent to the primary tumor, hormone-sensitive and hormone-refractory cancerous tissues." (PMID 19025630, 2008).
tumor (continued). "Interestingly, OAT's expression pattern in our tumor samples does not suggest AR-mediated stimulation, but rather repression, possibly reflecting interactions of AR signaling with input from other cell types or components of the extracellular matrix, which only occur in vivo." (PMID 17553165, 2007). "Furthermore, the AR expression in prostate and testes was not affected by treatment of mice with the siRNA selective for the human AR mRNA whereas this siRNA efficiently silenced AR in the human tumor cells and inhibited their growth in vivo." (PMID 17925854, 2007). "CCK-8 assays were performed to assess the impact of CDRs silencing on cell growth, which demonstrated a significant tumor cell growth inhibition effect in both C4-2 and PC3 cells regardless of the AR signaling activity." (PMID 41492471, 2026). "To facilitate mechanistic and pharmacologic studies, we established NCI-LYM-1, a patient-derived organoid/PDX from an AR-negative, ASCL1+/SYP+ lymph node metastasis, which faithfully recapitulates the donor tumor’s molecular and phenotypic features." (PMID 41542660, 2026). "Age, tumor size, tumor grade (1 vs. 2 vs. 3), histologic type, MAI10, AR-Manual, and treatment type were not significant." (PMID 39851328, 2025). "In our case, similar to other reports, the tumor was positive for CK7 and AR, and negative for CK20 and p63." (PMID 40724566, 2025). "As a result, for GPX4, but not AR, inhibition led to ferroptosis in LAR tumours, highlighting the importance of this specific metabolic target." (PMID 40136651, 2025). "Given the poor subcutaneous tumor take rate of our cellular model of choice—SNU-475 cells, which express only AR-SVs—we were limited to an adapted HFA model as opposed to a traditional subcutaneous xenograft model." (PMID 40805231, 2025). "The tumor cells were negative for calponin, carcinoembryonic antigen (CEA), and androgen receptor (AR)." (PMID 40677284, 2025). "Primary ductal adenocarcinoma (PDA) was ruled out as Androgen receptor (AR) and GCDFP-15 were negative in the present tumour cells favouring a diagnosis of adenocarcinoma NOS than PDA in which 90–95 % cases are reported to be positive for these markers." (PMID 40822511, 2025). "We successfully grew tumor chunks from new PDX line LTL706B in mouse renal capsules and then confirmed immunopositivity for PCa markers (AR, KRT8, and PSMA) and absence of CDK12." (PMID 39368479, 2024). "IHC to detect the N-terminus of AR revealed that AR is absent in the patient lymph node metastatic biopsy and CU-PC01 PDX tumours analysed at the early (P1) and late (P5) passage, as well as post-cryopreservation (P2-cyro)." (PMID 38667288, 2024). "The AR antagonist, ENZ demonstrated significant inhibition of tumor organoid growth only in samples cultured with DHT but not in those cultured without DHT." (PMID 38336745, 2024). "Correlation of AR expression with DCIS type, DCIS grade, tumor location, and presence or absence of comedo necrosis." (PMID 39439618, 2024). "Our data show that overexpressing AR-V7, but not AR-FL, in CRPC cells promotes tumor cell invasion into blood vessels and induces osteoblastic bone lesions in vivo." (PMID 38687617, 2024). "While CRPC with altered AR signaling (such as 22Rv1) is not sensitive to SupraT, hyperinduction of castration-responsive genes by MKI resembles SupraT in producing a strong tumor-suppressive effect." (PMID 38546787, 2024). "In support, IHC to detect PSA and PSMA that are directly or indirectly regulated by AR, respectively, revealed that CU-PC01 PDX tumours are PSA and PSMA negative." (PMID 38667288, 2024). "AR detected by IHC showed low expression in 60 cases of human BLCA and their adjacent normal tissues and 60 mouse tumour tissues, and no sex difference was found." (PMID 37328487, 2023). "Enobosarm is a non-steroidal selective androgen receptor modulator that, in AR-positive TNBC tumors, showed an ability to inhibit tumor growth." (PMID 37835396, 2023).
tumor (continued). "AR and GCDFP15 expression in the original tumor of YCU-SDC-20 was not confirmed in PDXs and orthotopically transplanted PDOs, but their expression was retained in orthotopically transplanted PDXOs." (PMID 36538240, 2023). "Based on the hormonal dependency of PCa tumours, expression analysis of METTL1, WDR4 and AR was performed, but no significative correlation was found between METTL1, WDR4 and AR expression." (PMID 37516825, 2023). "Immunophenotypically, the tumor was positive for Cytokeratins Oscar and 7, GATA3, GCDFP, HER2, and an androgen receptor but negative for CK20, S100, p40, Melan A, CDX2, TTF1, ER, SATB2, DOG1, synaptophysin, and chromogranin." (PMID 37886914, 2023). "RNA-seq performed on tumor biopsies from CRPC patients with resistance to enzalutamide followed by GSEA allowed researchers to discover altered pathways and reduced AR function, as well as an activated stemness program in non-responders." (PMID 35682963, 2022). "Of note, MALAT1 expression levels were increased in docetaxel (DTX)-resistant AR-negative PC3 and DU-145 cells, and DTX-resistant PCa patient tumours, and its overexpression enhanced DTX-chemoresistance in vivo." (PMID 35159022, 2022). "However, there was a difference in tumor grade between the two groups with the AR positive group having a greater percentage of grade 2 tumors (25% vs 2.6%), and a lesser percentage of grade 3 tumors (75% vs 97.4%) when compared to the AR negative group (p=0.008)." (PMID 35711833, 2022). "Immunohistochemical analysis revealed that this tumor was positive for PSA and androgen receptor (AR) and negative for chromogranin and synaptophysin, suggesting that the metastatic lesion unlikely had neuroendocrine differentiation." (PMID 35183184, 2022). "To understand the role of core transcription factors in AR-negative CRPC, we profiled OCT1 binding in a patient-derived model and identified two OCT1-target genes that promote the migration and/or tumor growth of AR-negative PC." (PMID 35413990, 2022). "Our validation of the SPT-R signature in an extended PDX cohort correctly identified 4 additional NR tumors, and all NEPCs and double-negative PC PDX models that do not express AR had low SPT-R signature scores, indicating an SPT NR tumor." (PMID 35603787, 2022). "The AR cistrome, or genome-wide binding sites, is not static, and clinical ARBS display remarkable plasticity and significant reprogramming during both tumor initiation and disease progression." (PMID 35269520, 2022). "A high prevalence of AR expression (91.5%) in BC HER+ was observed, with minimal differences between luminal and non-luminal tumor." (PMID 35052843, 2022). "However, the AR blocker enzalutamide could not completely reproduce the effect of AR knockdown, and the drug could not affect the growth and ER expression of tamoxifen–resistant cells and endocrine–resistant xenograft tumor models." (PMID 36556209, 2022). "The DU145 tumor model, representing aggressive CRPC, does not express AR and is radiation resistant." (PMID 35349486, 2022). "The reason is that the AR-siRNA delivered into PCs could inhibit the expression of AR protein, thereby interfering with AR-dependent gene expression and inhibiting the proliferation and metastasis of PC cells, rather than directly inhibiting or killing tumor cells." (PMID 35631549, 2022). "Further supporting the utility of GCN2 as a therapeutic target for PCa, a small molecule inhibitor of GCN2 significantly slowed tumor growth in both CDX and PDX models of androgen-sensitive and castration-resistant disease irrespective of AR status." (PMID 36107759, 2022). "To profile the expression of AR mRNA in urothelial bladder tissue, we performed a microarray analysis on NMIBC (CIS, and tumours of Ta and T1 stage), MIBC (tumours of T2, T3 and T4 stages) and nonmalignant bladder urothelial specimens." (PMID 33797847, 2021).